BMP1 (bone morphogenetic protein 1)
Description:
Metalloprotease that plays key roles in regulating the formation of the extracellular matrix (ECM) via processing of various precursor proteins into mature functional enzymes or structural proteins. Thereby participates in several developmental and physiological processes such as cartilage and bone formation, muscle growth and homeostasis, wound healing and tissue repair. Roles in ECM formation include cleavage of the C-terminal propeptides from procollagens such as procollagen I, II and III or the proteolytic activation of the enzyme lysyl oxidase LOX, necessary to formation of covalent cross-links in collagen and elastic fibers. Additional substrates include matricellular thrombospondin-1/THBS1 whose cleavage leads to cell adhesion disruption and TGF-beta activation. [Isoform BMP1-3]: Plays an important role in bone repair by acting as a coactivator of BMP7.
Synonyms: BMP-1; PCP; PCOLC; OI13; TLD
Tractability: Small molecule: a structure with a bound ligand is known; a high-quality ligand is known; it belongs to a druggable protein family. Antibody: UniProt places it where antibodies can reach, with high confidence; its Gene Ontology location is reachable by antibodies, with high confidence; UniProt predicts a signal peptide or a membrane-spanning region. PROTAC: ubiquitination databases record sites on it; its protein half-life has been measured; a small molecule that binds it is known.
Target class: Enzyme; Metallo protease M12A subfamily; Metallo protease; Protease; Metallo protease MAM clan
Chemical probes: UK 383367 (high quality)
Gene: Protein-coding gene on chromosome 8 (22,165,140 to 22,212,326, forward strand). Ensembl gene ENSG00000168487.
Subcellular location: Golgi apparatus, trans-Golgi network; Secreted, extracellular space, extracellular matrix; Secreted; Secreted (Isoform BMP1-3)
Pathways (Reactome):
Extracellular matrix organization: Anchoring fibril formation; Collagen biosynthesis and modifying enzymes; Crosslinking of collagen fibrils; Degradation of the extracellular matrix
Transport of small molecules: HDL assembly
Gene Ontology:
Molecular function: identical protein binding; peptidase activity; protein binding; metalloendopeptidase activity; metallopeptidase activity; serine-type endopeptidase activity; calcium ion binding; zinc ion binding
Biological process: positive regulation of cartilage development; proteolysis; cartilage condensation; collagen fibril organization; dorsal/ventral pattern formation; protein processing; skeletal system development
Cellular component: extracellular region; Golgi apparatus; vesicle
Genetic constraint (gnomAD): Loss-of-function variants: 63 observed, 120 expected, observed/expected ratio (o/e) 0.52, 90% interval 0.43 to 0.65. The upper end of that interval is the gene's LOEUF score, 0.65, which puts it in group 2 of 6, group 1 being the genes least tolerant of losing a copy. Missense variants: 1,183 observed, 1,408.4 expected, observed/expected ratio (o/e) 0.84, 90% interval 0.8 to 0.88. Synonymous variants: 536 observed, 550.64 expected, observed/expected ratio (o/e) 0.97, 90% interval 0.91 to 1.04.
Homologues: Orthologues: chimpanzee BMP1 (99% identical), macaque BMP1 (99% identical), pig BMP1 (97% identical), dog BMP1 (97% identical), guinea pig BMP1 (96% identical), rat Bmp1 (96% identical), mouse Bmp1 (96% identical), rabbit BMP1 (90% identical), tropical clawed frog bmp1 (78% identical), zebrafish bmp1a (78% identical), zebrafish bmp1b (72% identical). Paralogues in human: TLL2 (75% identical), TLL1 (73% identical), CUBN (18% identical), CNTNAP2 (15% identical), CNTNAP4 (15% identical), CNTNAP5 (14% identical), CNTNAP3 (14% identical), CNTNAP3B (14% identical), F8 (14% identical), CNTNAP1 (14% identical), MEP1B (13% identical), F5 (12% identical), and 23 more.
Diseases named in the same sentence as BMP1 in open-access papers:
BMP1 is named in the same sentence as 105 diseases in open-access papers, as found by Europe PMC text mining. Sharing a sentence is not in itself a finding about the gene and the disease. The quoted sentences say what the papers report.
osteogenesis imperfecta (19 papers, 2015 to 2025). Osteogenesis imperfecta (OI) comprises a heterogeneous group of genetic disorders characterized by increased bone fragility, low bone mass, and susceptibility to bone fractures with variable severity. "Mutations in bone morphogenetic protein 1 (BMP1) have also been identified as a rare cause of recessive osteogenesis imperfecta." (PMID 38315213, 2024). "Although very few patients with BMP1-associated osteogenesis imperfecta have been identified, in a biopsy study of one patient, thick osteoid seams were present, with hypermineralization in the mineralized bone." (PMID 38315213, 2024). "For example, the module gene BMP1 (Bone Morphogenic Protein 1) causes osteogenesis imperfecta, which is associated with short stature." (PMID 31471613, 2019). "In humans, mutations in BMP1 result in a rare recessive form of the brittle bone disease Osteogenesis Imperfecta (OI)." (PMID 28884682, 2017). "Mutations in BMP1 lead to osteogenesis imperfecta, underscoring its significance in bone formation." (PMID 40332455, 2025). "In previous experiments, the knockout of BMP1 resulted in osteogenesis imperfecta in mice." (PMID 33732164, 2021). "These disorders are categorized into major clinical groups, such as Skeletal Dysplasias (e.g., analysis of genes like ACAN, ACP5, and ACVR1), Osteogenesis Imperfecta (COL1A1, COL1A2, BMP1), Metabolic Disorders (ACE, AGT, BICC1), and Cardiomyopathies, among others." (PMID 40282387, 2025). "While Bmp1 and Aclp mutants provide insight into mechanisms of GS in the mouse, they do not phenotypically model BMP1 and AEPB1 (ACLP) autosomal recessive mutations in humans, which cause Ehlers‐Danlos syndrome, classic‐like 2 and osteogenesis imperfecta, type XIII, respectively." (PMID 39319771, 2025).
gastric cancer (13 papers, 2015 to 2025). A primary or metastatic malignant neoplasm involving the stomach. "BMP-1 was reported to be up-regulated in gastric cancer and associated with poor survival and distant metastasis." (PMID 35036081, 2022). "High BMP1 expression has been associated with poor prognosis in gastric cancer." (PMID 36134447, 2022). "Of note, ECM remodeling-related proteins, including BMP1 and serpin family members, are involved in gastric cancer invasion and metastasis." (PMID 35409069, 2022). "A high BMP1 expression reflects a poor prognosis in human gastric cancer and clear cell renal cell carcinoma." (PMID 36267461, 2022). "The gene analysis of samples from patients with gastric cancer indicated that a high ELK3 expression is positively correlated with BMP1, LOXL2, SNAI1, SERPINF1, DCN, and NID1 expression, all of which are closely associated with a poor prognosis." (PMID 35409069, 2022). "Patients with gastric cancer with a high expression of BMP1, LOXL2, SNAI1, SERPINF1, DCN, and NID1 had a poor prognosis." (PMID 35409069, 2022). "The analysis of various gastric cancer cell lines and gastric cancer patient samples also revealed a positive association between ELK3 and BMP1, LOXL2, SNAI1, SERPINF1, DCN, and NID1, and these genes were associated with a poor prognosis." (PMID 35409069, 2022). "In recent years, BMP1 was found to be upregulated in gastric cancer, lung cancers, osteosarcoma, and colon cancer." (PMID 31155610, 2020). "As expected, in the late-stage gastric cancer patients, the expression level of BMP1 correlated with survival outcome." (PMID 29720137, 2018). "We first determined the expression level of BMP1 in gastric cancer cell lines AGS, MKN28, and MKN45 by quantitative RT-PCR and immunoblotting." (PMID 29720137, 2018). "In vitro, suppression of BMP1 inhibits the mobility of the gastric cancer cell lines, indicating a role of BMP1 in metastasis." (PMID 29720137, 2018). "In order to identify the role of BMP1 in the progression of gastric cancer, in vitro investigation was carried out using established gastric cancer cell lines." (PMID 29720137, 2018). "Our finding indicates that upregulation of BMP1 is correlated with the poor survival of gastric cancer patients." (PMID 29720137, 2018). "Together, the result indicates that BMP1 inhibition reduces the mobility of gastric cancer cell line and supports the notion that BMP1 plays a role in metastasis of gastric cancer." (PMID 29720137, 2018). "Our result indicated a potential use of either BMP1 or TGF-β inhibitors as a preventative or adjuvant treatment for TGF-β active gastric cancer." (PMID 29720137, 2018). "A tumor suppressor role of miR-194 was also described for gastric cancer and lung cancer, though bone morphogenetic protein 1 (BMP1) and the cyclin-dependent kinase inhibitor p27(kip1) were the targets of miR-194 in these cancers." (PMID 26380245, 2015). "Furthermore, overexpression of BMP1 was investigated in multifarious carcinomas, such as lung cancer, gastric cancer, and osteosarcoma." (PMID 36267461, 2022). "Although several studies have reported the oncogenic role of BMP1 in other cancers, including non-small-cell lung cancer and gastric cancer, the role of BMP1 in gliomas is unknown." (PMID 35528238, 2022). "It was reported that the up-regulation of BMP1 may indicate the poor prognosis of gastric cancer, osteosarcoma, renal clear cell carcinoma, and other tumors." (PMID 33859939, 2021). "In recent years, BMP1 upregulation may increase cancer invasiveness in gastric cancer, lung cancers, osteosarcoma, and colon cancer." (PMID 31155610, 2020). "BMP1 is upregulated in gastric cancer and is correlated with poor patient survival." (PMID 29720137, 2018). "We first determined whether BMP1 regulated the activation status of the TGF-β signaling pathway in the established gastric cancer cell line." (PMID 29720137, 2018).
gastric cancer (continued). "Inhibition of BMP1 suppressed mobility in gastric cancer cell lines, suggesting that BMP1 upregulation may increase cancer invasiveness." (PMID 29720137, 2018). "Besides previously reported markers, first reported in this study is the drastic increase of BMP1 expression in gastric cancer." (PMID 29720137, 2018). "Suppression of BMP1 reduced gastric cancer mobility in vitro." (PMID 29720137, 2018). "The ELK3 expression in gastric cancer cells and human gastric cancer samples positively correlated with that of BMP1, LOXL2, SNAI1, SERPINF1, DCN, and NID1, suggesting that this gene signature may be predictive molecular markers for aggressive gastric cancer progression." (PMID 35409069, 2022). "Notably, the analysis of patients with gastric cancer indicated the marked positive regulation of ELK3 and BMP1, LOXL2, SNAI1, SERPINF1, DCN, and NID1 gene expression, suggesting a significant positive correlation between ELK3 and ECM remodeling-associated genes in gastric cancer." (PMID 35409069, 2022). "The analysis of data from TCGA and GTEx revealed that ELK3 and BMP1, and LOXL2 were highly expressed in the gastric cancer samples compared with the healthy samples." (PMID 35409069, 2022). "First, the correlation between ELK3 expression and BMP1, LOXL2, SNAI1, SERPINF1, DCN, and NID1 expression was analyzed in 19 different gastric cancer cell lines." (PMID 35409069, 2022). "Our analysis, thus, showed that abnormal expression of BMP1, COL1A1, STAT3, GATA6, SOX2 and FOXA2 forms an ubiquitous molecular signature of gastric cancer patients in Southwestern Taiwan." (PMID 29720137, 2018). "Activation of STAT3 induced by H. pylori infection was shown to promote gastric oncogenesis, but the role of BMP1 in gastric cancer has not been examined before." (PMID 29720137, 2018). "Interestingly, it has been demonstrated that BMP1 is involved in the metastasis of gastric cancer and non-small cell lung cancer." (PMID 35155451, 2021).
lung cancer (9 papers, 2010 to 2025). A malignant neoplasm involving the lung. "It is widely accepted that the expression of lncRNAs are tissue-specific, suggesting that lnc-BMP1-1 is a potential biomarker for lung cancer screening." (PMID 31901898, 2020). "Similarly suppression of BMP-1 expression reduces the activity of TGF-β, downregulates MMP2/MMP9 expression and decreases the invasion of lung cancer cells." (PMID 39792296, 2025).
clear cell renal cell carcinoma (7 papers, 2019 to 2023). "The high expression of BMP1 is a poor prognostic factor in patients with renal clear cell carcinoma, and knocking down BMP1 inhibits the proliferation and invasion of renal clear cell carcinoma in vitro and in vivo." (PMID 37006234, 2023).
breast carcinoma (5 papers, 2018 to 2025). "We here observed that inhibition of TGF-β and BMP-1 activity induces only partially similar effects in metastatic murine mammary carcinoma cells as well as MDA-MB-231 and MCF-7 human mammary cancer cells." (PMID 39792296, 2025). "Effects of specific BMP-1 inhibitor on liver and brain metastatic murine mammary cancer cells (4TLM and 4TBM), as well as on human mammary cancer MDA-MB-231 and MCF-7 cells, were examined and compared with the results of TGF-β inhibition." (PMID 39792296, 2025). "For example, LOX/BMP1 mediates the malignant progression of anaplastic thyroid carcinoma, and BMP1 is considered a promoting factor in breast cancer and bone metastasis." (PMID 36267461, 2022). "Specifically, inhibition of BMP-1 activity markedly enhanced anti-proleferative effects of doxorubicin, a commonly used chemotherapeutic drug, in both highly metastatic murine mammary and human mammary cancer cells." (PMID 39792296, 2025). "To test this hypothesis we examined the effects of specific BMP-1 inhibitor alone and in combination with doxorubicin on liver and brain metastatic murine mammary cancer cells (4TLM and 4TBM, respectively)." (PMID 39792296, 2025). "In this study, we have highlighted the significance of TGFβ-1, IL19, CXCR4, BMP1, IL1A, VCAN, PDK1, and WNT2 in breast cancer pathology." (PMID 41348904, 2025). "By employing UALCAN, we examined the pattern of expression for TGFβ-1, IL19, CXCR4, BMP1, VCAN, and WNT2 in breast cancer." (PMID 41348904, 2025). "We compared the TGFβ-1, CXCR4, IL19, BMP1, VCAN, and WNT2 expression in different subtypes of breast cancer, and the results demonstrated that BMP1, and WNT2 were consistently overexpressed in HER-2 subtype." (PMID 41348904, 2025). "Expression levels of these genes were also examined across various pathological stages of breast cancer, where a stage-dependent increase was observed particularly for CXCR4, BMP1, VCAN, and WNT2." (PMID 41348904, 2025). "It was shown that TGF-β2 increases BMP-1 secretion: indeed, we found that BMP-1 inhibition decreases TGF-β secretion from both human and murine mammary cancer cells demonstrating a positive feed-back among BMP-1 and TGF-β." (PMID 39792296, 2025). "The expression pattern of TGFβ-1, IL19, CXCR4, BMP1, VCAN, and WNT2 in different molecular subclasses of Breast Cancer revealed that TGFβ-1, IL19, CXCR4, BMP1, VCAN, and WNT2 mRNA levels are higher in luminal A followed by luminal B, HER2 and Basal like respectively." (PMID 41348904, 2025). "In accordance, BMP-1 secretion of non-metastatic 67NR mammary cancer cells was much lower." (PMID 39792296, 2025). "Importantly inhibition of BMP-1 activity enhanced anti-tumoral effects of doxorubicin in both murine and human metastatic mammary cancer cells, while we did not observe similar changes following TGF-β inhibition." (PMID 39792296, 2025). "In addition, secretion of bone morphogenetic protein 1 (BMP-1), which is crucial for the proteolytic release of TGF-β, was markedly high in metastatic mammary cancer cells compared to non-metastatic cells." (PMID 39792296, 2025). "In addition, the role of BMP-1 inhibition on MDA-MB-231 metastatic human TNBC cells were determined, while MCF-7 cells were used to model non-metastatic hormone receptor positive human mammary carcinoma." (PMID 39792296, 2025).
glioma (5 papers, 2016 to 2022). A benign or malignant brain and spinal cord tumor that arises from glial cells (astrocytes, oligodendrocytes, ependymal cells). "Lastly, we confirmed that bone morphogenetic protein 1 (BMP1), which is part of the risk signature, is strongly linked with malignant characteristics of gliomas." (PMID 35528238, 2022). "Thus, we functionally verified the effects of BMP1 on gliomas and showed that BMP1 is strongly associated with gliomas' invasive behaviors in vitro." (PMID 35528238, 2022). "Taken together, these results suggest that BMP1 is functionally required for multiple malignant characteristics in gliomas." (PMID 35528238, 2022). "For further verification, shRNAs targeting BMP1 (shBMP1 #1 and shBMP1 #2) were introduced into U87 glioma cells." (PMID 35528238, 2022). "It was previously reported that BMP1 was involved in multiple signaling pathways of GBM and was associated with a poor prognosis for glioma patients." (PMID 32214002, 2020). "As previously reported, miR210HG levels were higher in glioma patients and predicted complementary binding with BMP1." (PMID 29156779, 2017). "Second, the relationship between lncRNA miR210HG and mRNA BMP1 in glioma patients must be established further with research." (PMID 27673330, 2016). "As expected, the result showed that BMP1 is highly expressed in glioma samples." (PMID 35528238, 2022). "In addition to bioinformatics analyses, we functionally verified the oncogenic role of bone morphogenetic protein 1 (BMP1) in gliomas in vitro." (PMID 35528238, 2022). "Finally, the pathobiological mechanism of miR210HG expression and its relationship with BMP1 in glioma patients is unclear." (PMID 27673330, 2016). "However, the expression and oncogenic role of BMP1 in gliomas have been rarely studied." (PMID 35528238, 2022). "BMP1 is involved in many signaling pathways in GBM and correlate with poor prognosis in glioma patient." (PMID 30344926, 2018).
atherosclerosis (4 papers, 2017 to 2024). A disease characterized by the build-up of fatty material and calcium deposition in the arterial wall resulting in partial or complete occlusion of the arterial lumen. "BMP1 is a potent pro-collagen cleavage protease that is involved in atherosclerosis; in fact, its reduction decreases vascular wall calcification." (PMID 28757161, 2017). "BMP signalling is activated by BMP1, which degrades BMP antagonist chordin, resulting in atherosclerosis." (PMID 29596467, 2018).